RNF20 (ring finger protein 20)
Diseases named in the same sentence as RNF20 in open-access papers (continued):
Sharing a sentence is not in itself a finding about the gene and the disease.
cancer (continued). "Our work could potentially provide alternative strategies to treat bleomycin-resistant cancer using inhibitors targeting RNF20 or its interaction with hRad51." (PMID 37230987, 2023). "In addition to the extensive cancer development research using mainly in vitro methods, there are several important studies that used mouse models to determine the roles of RNF20/40 in this process." (PMID 35954248, 2022). "Because much remains to be clarified regarding relationships among the cancer epigenome, gene expression regulatory mechanisms and DNA repair processes, the roles of H2Bub1 and RNF20/40 in cancer-related chromatin remodeling are of considerable and increasing interest." (PMID 33199825, 2021). "In conclusion, up-regulation of RNF20/40-mediated up-regulation of H2Bub1 may down-regulate cancer progression and may be a therapeutic target for cancer prevention and treatment." (PMID 29934362, 2018). "However, several additional in vitro, in vivo, and transgenic rodent studies will determine if RNF20/40 and H2Bub1 can be used as a promising target to be exploited for the prevention and treatment of cancer." (PMID 29934362, 2018). "The exact molecular role of RNF20 varies in different types of cancers; therefore it is valuable to determine the role for DUBs, protein kinases, and/or pharmacological drugs in modulating RNF20 levels that may provide clinical benefits." (PMID 29934362, 2018). "Remarkably, diminished expression of USP22 and/or overexpression of RNF20/40 at the mRNA level is observed in 38% of primary tumors in colorectal adenocarcinoma, a cancer type characterized by a very high prevalence of chromosome instability (up to 85% of cases)." (PMID 29210986, 2017). "Physiologically, such as during normal development, RNF20/40 might respond to H2Bub1-dependent DNA damage repair, whereas pathologically in cancers, RNF20/40 might act, at least in part, through ubiquitylation of nonhistone proteins to play roles in cancer development, progression, and metastasis." (PMID 33199825, 2021). "Thus, future studies are needed to reveal whether RNF20–SREBP-1c axis would play central roles in various cancers." (PMID 29138263, 2017). "Further studies of RNF20 and RNF40 as potential targets for cancer therapy are warranted and urgently needed." (PMID 33199825, 2021). "H2Bub1, RNF20 and/or RNF40 have been investigated in numerous cancer tissues, including breast, ovarian, colorectal, lung, gastric, kidney and parathyroid." (PMID 33233707, 2020). "The miR-221-3p targets genes at early stage such as Annexin A1 (ANXA1), Cyclin Dependent Kinase Inhibitor 1B (CDKN1B), and multiple genes during advance-stage cancer such as CDKN1B, PTEN, Ring Finger Protein 20 (RNF20), Estrogen Receptor 1 (ESR1) and AKT3." (PMID 31756185, 2019). "The decreased expression of RNF20 enhances the transcriptional effects of EGF, leading to an increase in transformation, migration and metastasis of cancer cells and tumourigenesis." (PMID 26466379, 2015). "Therefore, addressing these questions will hopefully advance our understanding on the role of RNF20/40 and H2Bub1 in chromatin remodeling during transcription and DNA DSB repair, and the potential of epigenetics based therapies for cancer." (PMID 29934362, 2018). "Whether defective Rnf20 or Rnf40 leads to defective cohesion and CIN in human cells, and whether this contributes to tumorigenesis initiation and progression, is worth pursing in order to reveal the genetic basis of CIN in cancers." (PMID 29058668, 2017).
cancer (continued). "RNF20/40 is considered to be the major E3 ubiquitin ligase that catalyzes H2Bub1; however, whether RNF20/40-mediated H2Bub1 is fully responsible for various cancer phenotypes is not fully understand." (PMID 33199825, 2021).
infection (5 papers, 2013 to 2025). The state of being infected such as from the introduction of a foreign agent such as serum, vaccine, antigenic substance or organism. "Moreover, transcriptome sequencing revealed that RNF20 expression is upregulated in chickens following infection with highly pathogenic avian influenza." (PMID 39998124, 2025). "Hematoxylin–eosin staining revealed increased immune cell infiltration and muscle damage in RNF20 knockdown chickens compared with WT controls after NDV-GFP or H9N2 infection." (PMID 39998124, 2025). "While in the late stages of infection, RNF20 translocates out of the nucleus and catalyzes the ubiquitinated degradation of MDA5." (PMID 39998124, 2025). "Specifically, in uninfected and during early infection, RNF20 regulates MDA5 transcription in the nucleus." (PMID 39998124, 2025). "We then selectively deleted RNF20 in T‐Rnf20Flox/Flox MEF cells by culturing the cells in the presence of 4‐OH tamoxifen during 3 continuous days pre infection (hereafter referred to as Rnf20−/−)." (PMID 34155716, 2021). "In addition, global and ISG-specific levels of H2Bub1 can be regulated by type I IFN signaling during infection with human adenovirus as well, in a manner depending on human Bre1/RNF20 and the viral E1A protein." (PMID 35933402, 2022). "Additionally, infections with VSV-GFP, Newcastle disease virus (NDV-GFP), and the RNA virus nucleic acid mimic poly (I: C) result in a significant upregulation of RNF20 expression in DF-1 cells." (PMID 39998124, 2025). "Mechanistically, RNF20 is located in the nucleus, where it maintains the basic expression and regulates the inducible expression of MDA5 to establish immune defense during the early infection phase." (PMID 39998124, 2025).
adenocarcinoma (2 papers, 2025). A common cancer characterized by the presence of malignant glandular cells. "Consistent with findings in MLE12 cells, we observed that the ablation of a single RNF20 allele in the human A549 adenocarcinoma cell line led to increased levels of HIF1α and γH2AX." (PMID 40436847, 2025). "Consistent with this, we found significantly decreased RNF20 protein levels in patients with SCLC and a progressive loss in high-grade adenocarcinoma AD." (PMID 40436847, 2025).
inflammation (2 papers, 2021 to 2025). Aberrant reaction of the microcirculation characterized by movement of fluid and leukocytes from the blood into extravascular tissues. "Thus, the intestinal deletion of Rnf20 and Rnf40 in murine IECs is associated with gene expression profiles induced in murine and human intestinal inflammation." (PMID 34088983, 2021).
metabolic disease (2 papers, 2021 to 2025). A congenital disorder (due to inherited enzyme abnormality) or acquired (due to failure of a metabolically important organ) disorder resulting from an abnormal metabolic process. "Modulating Rnf20 regulated signaling cascades may contribute a potential target for the therapeutic invention of adipose tissue dysfunction and related metabolic diseases." (PMID 32797353, 2021).
endocrine disorders (1 paper, 2020). "Consistent with our speculation, heterozygous knockout of Rnf20 in mice leads to endocrine disorders." (PMID 32443664, 2020).
renal diseases (1 paper, 2023). "The expression of RNF20 in the kidney contributes to the decline in renal function and is believed to have significant implications for understanding renal diseases involving metabolic factors." (PMID 38068817, 2023).
RNF20 also shares sentences with these, for which no sentence is quoted: clear cell Renal Cell Carcinoma (2 papers); lung adenocarcinoma (2); seminoma (2); breast (1); endocervical adenocarcinoma (1); hepatocellular carcinoma (1); immunodeficiency (1); lymphoma (1); neurodegenerative disease (1); pancreatic carcinoma (1); serous ovarian carcinomas (1); steatosis (1).